SOX9 (SRY-box transcription factor 9)
Diseases named in the same sentence as SOX9 in open-access papers (continued):
Sharing a sentence is not in itself a finding about the gene and the disease.
tumor (continued). "As a substantial expression of SOX9 positive cells was observed in the tumor microenvironment, the percentage of SOX9 positive cells and staining intensity were quantified using the QuPath software." (PMID 38275880, 2024). "Specifically, SOX9 promotes tumor cells to non‐NE differentiation, such as bone or cartilage differentiation, while SOX2 promotes the determination of the NE lineage." (PMID 39372390, 2024). "The immunohistochemical study shows cytoplasmic reactivity to S100 protein and nuclear SOX9 reactivity, consistent with the cartilaginous nature of the tumor." (PMID 39489866, 2024). "In some cancers, including HNSCC, SOX9 has been reported to exhibit both tumor-promoting and tumor-suppressive activities." (PMID 38275880, 2024). "HBMSCs-Exo with miR-145-5p inhibitor promoted tumor volume and weight, which was also significantly reversed by inhibition of SOX9." (PMID 39039505, 2024). "In recent years, a number of reports have elucidated the involvement of SOX9 either as an oncogene or as a tumor suppressor gene." (PMID 38275880, 2024). "Higher expression of the SOX9 gene in the LUSC tumor tissues was verified when compared with the matched normal tissues." (PMID 37020558, 2023). "Studies have shown that SOX9 can interact with a variety of downstream proteins and exhibit stimulatory or inhibitory activity in different types of tumour cells." (PMID 37328795, 2023). "Based on the RT-qPCR results, it was evident that the SOX9 expression level was significantly increased in the Tumor group compared with that in the Normal group in the collected clinical samples (P < 0.05)." (PMID 37919693, 2023). "More than 90% of tumor cells showed nuclear expression of Sox9, which is a master regulator of chondrogenic differentiation." (PMID 37212282, 2023). "As a proto-oncogene or tumor suppressor gene, SOX9 can induce epithelial–mesenchymal transition (EMT) by regulating the tumor microenvironment (TME) to acquire stem cell characteristics, which are dependent on cancer type." (PMID 37020558, 2023). "This study identified SRY-box 9 (Sox9) activation as a common feature of tumor initiation in all the tested models." (PMID 37894295, 2023). "Another study showed that ATP-modulated SOX-9 signaling via P2Y2 receptors is a crucial mechanism in mediating tumor metastasis." (PMID 36750864, 2023). "Of note, we observed a reduced presence of double PanCK+-SOX9+ tumor cells in 6-thio-dG-treated mice compared to LLC control mice." (PMID 37085672, 2023). "It is worth noting that the expression and stability of SOX9 are related to maintaining tumor stem cell characteristics." (PMID 37907984, 2023). "For further validation of these prognostic markers, we analyzed S100B and SOX9 protein in an ONB tumor by IHC." (PMID 37377616, 2023). "And the key roles of SOX2 and SOX9 in the regulation of cancer stemness and tumor metastasis have been well-documented in previous studies." (PMID 36902193, 2023). "In a hypoxic environment, the upregulated transcription factor SOX9 in the tumor increased the synthesis of miR-204-3p, but the total content of miR-204-3p in tumor cells was decreased." (PMID 36810326, 2023). "In the current study, we thoroughly analyzed SOX9 expression in normal and tumor tissues, matched healthy tissues, and performed correlation analysis with immunomodulators and immune cell infiltration in pan-cancer." (PMID 37020558, 2023). "In the progression of breast cancer, SOX9 triggers tumorigenesis by facilitating the immune escape of tumor cells." (PMID 37020558, 2023). "In the current study, we comprehensively analyzed the expression of SOX9 in normal tissues, tumor tissues and their matched healthy tissues in pan-cancers." (PMID 37020558, 2023). "As expected, the treatment of mucosa and tumor cells with anti-KRAS antibodies led to a decrease in SOX9 expression." (PMID 37051535, 2023).
tumor (continued). "SOX9, Sex determining region Y-box 9, was reported to be a potential tumor diver, regulated by various miRNAs and reactions like methylation, phosphorylation, and acetylation." (PMID 36854894, 2023). "To further investigate the role of SOX9 in OS tumor growth in vivo, we performed immunohistochemistry (IHC) of Ki-67 (proliferative marker) and cleaved caspase 3 (apoptosis marker)." (PMID 37491298, 2023). "Herein, we showed that anti-KRAS antibody treated tumor cells have less intense SOX9 cytoplasmic and nuclear staining compared to untreated cells." (PMID 37051535, 2023). "In Inha testis tumour regions, the combination of low SOX9 protein levels and increased expression of steroidogenic components allude to cell identity changes consistent with this process." (PMID 37564373, 2023). "The data exhibited that SOX9 mRNA level was excessive both in tumor tissues and cancer cells when compared to the normal group." (PMID 36854894, 2023). "Some studies have pointed out that the expression level of SOX9 is correlated with tumor invasion, metastasis and patient survival." (PMID 37919693, 2023). "To determine the impact of TGFBR1 overactivation on cell identify, we performed immunostaining of SOX9 using testes from 1-month-old mice prior to gross tumor formation." (PMID 38067144, 2023). "The histological and growth characteristics of mesenchymal chondrosarcoma resemble the centripetal growth pattern of embryonic cartilage, and the tumor is also characterized by positive expression of Sox9, a master regulator of chondrogenesis." (PMID 37212282, 2023). "To test the effect of SOX9 depletion on OS tumor progression in vivo, we reduced the levels of SOX9 in SAOS2 cells using the two shRNAs and then transplanted cells into NOD-scid, IL2R gammanull (NSG) mice." (PMID 37491298, 2023). "CD significantly inhibits SOX9 expression in a variety of tumor cells and targeting SOX9 with CD is more promising as a strategy for cancer therapy." (PMID 37020558, 2023). "Previous studies have demonstrated that the SOX9 protein directs pathways involved in tumor initiation, proliferation, migration, metastasis and stem cell maintenance, thereby regulating tumorigenesis as an oncogene." (PMID 36123852, 2022). "Here we identified the miR-485-3p/SOX9 axis as a signaling pathway that promotes tumor progression in response to circSOX9." (PMID 35700516, 2022). "SOX9 is involved in tumor initiation through Wnt/β-catenin pathway as well as tumor invasion through activation of TGFb/Smad signaling." (PMID 35221802, 2022). "We also fitted multivariate Cox models including covariates of race, M stage, tumor differentiation, SOX9, where these variables had p-values less than 0.25 in univariate analysis." (PMID 35221802, 2022). "Recent research has revealed that SOX9 plays an important function in the control of the tumor microenvironment (TME)." (PMID 36303551, 2022). "Mechanistically, circ_0032821 upregulated the tumor promoter SRY-box transcription factor 9 (SOX9) by sequestering miR-515-5p." (PMID 35127685, 2022). "Confocal fluorescence IHC study showed higher SOX9 staining in tumor compared to matched mucosa cryosections, especially in tumor harboring KRAS G12D and G12V mutations." (PMID 34919787, 2022). "Multivariable analysis demonstrated that presence of metastasis (pM1) and SOX9 expression were predictors of poor prognosis, while better tumor differentiation was a predictor of good prognosis." (PMID 35221802, 2022). "Sox9 is a high-mobility group box transcription factor that plays critical roles during embryogenesis, differentiation, tumor initiation, invasion and stem cell self-renewal." (PMID 36180477, 2022). "Our experimental results demonstrated that cytoplasmic SOX9 plays a critical role in suppressing cancer stem cell death, as shown by complete suppression of sphere formation in vitro and tumor formation in vivo." (PMID 35159173, 2022).
tumor (continued). "SOX9 was found to be overexpressed in a wide range of human malignancies and its expression correlated with tumor aggressiveness." (PMID 35221802, 2022). "It has been shown that SOX9 is overexpressed in cancers of the skin, prostate, lung, and breast and contributes to tumor growth and invasion." (PMID 35884771, 2022). "SOX9 is known to work downstream of SOX2 to control the luminal progenitor cell content resulting in increased tumor initiation, drug resistance, and poor prognosis." (PMID 35906698, 2022). "On the contrary, one study found an inverse correlation between SOX9 expression and advanced tumor stage, vessel infiltration, nodal metastasis, and EBV infection." (PMID 35221802, 2022). "The positive association between the expression of DDR1 with genes SOX9, CTNNB1, or VANGL2 emphasizes its role in stemness and tumor aggressivity." (PMID 35664781, 2022). "TCGA-COAD public cohort also confirmed that SOX9 was higher in tumor tissue than that in adjacent tissue." (PMID 36159794, 2022). "Our research shows that the expression of miR-485-3p in NPC is down-regulated, and it exerts a tumor suppressor effect by targeting SOX9." (PMID 35700516, 2022). "Early studies have illustrated the diverse functions of the SOX9 gene, including embryonic development, sex differentiation, and cartilage formation, and promoting tumor proliferation, invasion, metastasis, and progression." (PMID 35586685, 2022). "Previous studies have shown that in a number of cancer types, SOX9 can function as an activator of EMT in tumor cells." (PMID 35884771, 2022). "For tumor-derived organoids cultured for 2 weeks, majority of the cells expressed SOX9/MKI67 (SOX9+ 41.6%, MKI67+ 77.5%, SOX9+MKI67+ 37.7%), but after long-term culture (2 months), less cells expressed SOX9 or MKI67." (PMID 35974387, 2022). "Earlier, it has been shown for a group of tumor types that the SOX9 factor affects cancer cell division, since SOX9 overexpression increases the proliferation of a group of cell lines, and the downregulation of SOX9 expression slows down the proliferation." (PMID 35884771, 2022). "Differentially expressed genes (DEGs) analysis showed a distinct transcriptional character in the CTCs although they shared some tumor-specific marker genes (such as TGFB1 and SOX9) with tumor cells in solid lesions." (PMID 35221332, 2022). "These tumor cells originate from Sox9+ cells, suggesting that Pten deletion induces the transformation of the Sox9+ cells." (PMID 35267473, 2022). "On the other hand, the expression of marker genes for other cell types, such as LYZ (Paneth cell marker) and SOX9 (intestine progenitor cells), were enriched in tumor epithelial cells and LYZ expression was further verified by IHC staining." (PMID 35974387, 2022). "In vivo, we observed an enhanced tumor formation capacity when SOX9-upregulated GNS166 cells were injected orthotopically in immunodeficient NOD-SCID mice." (PMID 35562901, 2022). "Analyses of the TCGA and GSE95132 paired tumor‐mucosa transcriptome datasets also revealed SOX9 to be significantly upregulated in tumor compared to matched mucosa." (PMID 34919787, 2022). "These in vitro and in vivo results demonstrated that SOX9 expression was required for the prevention of cancer cell death as well as for the promotion of cancer cell proliferation, consequently resulting in tumor growth." (PMID 35159173, 2022). "Supporting this is our finding that targeted deletion of LATS1/2 in Sox9-expressing cells using a Sox9CreERT2 model resulted in basal-like tumor development like that observed using a K8CreERT2 model." (PMID 36443313, 2022). "SOX9- and BCL11A-encoded proteins were both involved in inducing tumor initiation, proliferation, migration, and chemoresistance." (PMID 36092919, 2022).
tumor (continued). "An example that can be drawn from our present study is the overexpression of the SOX9 gene, which is considered a tumor progression factor." (PMID 35216085, 2022). "Immunohistochemistry using various tumor stem cell-specific markers, including acetaldehyde dehydrogenase 1, CD44, CD133, Nestin, NGFR, and SOX9, revealed short spindle-positive cells scattered within the tumor, suggesting the involvement of tumor stem cells." (PMID 36187098, 2022). "Co-immunofluorescent staining (IF) further validated that expression of GRK3 and SOX9 was dramatically increased in tumor tissues from the GRK3 OE group, compared to the NC group." (PMID 35996148, 2022). "Previously, we and others have reported that Hippo/YAP1 mediates CSC attributes and tumor progression through regulation of its downstream targets, such as SOX9, Birc5, and Cyr61." (PMID 35996148, 2022). "The most intensely SOX9 staining cells in the K-Ras G12V-induced lung primary adenocarcinomas were also the areas of tumor growth at invasive sites." (PMID 35205666, 2022). "We determined the effect of SOX9-silencing on tumor initiation by performing subcutaneous injections upon limiting dilution transplantation in immunocompromised mice in vivo." (PMID 35205666, 2022). "Through the IHC experiment, we found SOX9 was higher in the 50 tumor tissue than the 50 tumor adjacent tissue." (PMID 36159794, 2022). "The analysis using the ELDA software application revealed a diminished frequency of tumor-initiating/cancer stem cells in SOX9-silenced cells, with frequencies of 1/422,319 and 1/5,255,599 for the control and shSOX9 cells, respectively." (PMID 35205666, 2022). "By Integrating with the DNA mutation and RNA expression in CS3, we identified that SOX9, a specific marker of CS3, was higher in the tumor than tumor adjacent by IHC in the in-house cohort and public cohort." (PMID 36159794, 2022). "Herein, this finding in HCC not only expands the tumor pool where symmetrical cell division increases CSCs but also reveals a novel mechanism related to SOX9-induced CSCs properties in HCC." (PMID 35267473, 2022). "Herein, we found that SOX9 was higher in grade IV cases, linking its high levels to tumor malignancy." (PMID 35562901, 2022). "Consistently, restoration of EpCAM and Sox9 expression in JMJD2D-knockdown LCSCs partially rescued the subcutaneous tumor growth." (PMID 33434575, 2021). "The delayed tumor onset and low tumor incidence in the Sox9-Pten mice suggest that additional signals that promote tumorigenesis are present in the Alb-Pten livers but are absent in the Sox9-Pten livers." (PMID 34083580, 2021). "The positive correlation of SOX9 gene and protein level was observed and the tumor size and tumor invasive features were valuable in predicting SOX9 expression level in GH-producing pituitary tumors." (PMID 33736633, 2021). "In intrahepatic CCA, the expression level of SOX9 was correlated with tumor stage, that is, a low level of expression was detected in the early stage of the tumor and the high level was related to tumor invasion." (PMID 35201494, 2021). "Based on the analysis, the correlation of tumor invasive features with SOX9 tumor expression was significant." (PMID 33736633, 2021). "PTEN loss and liver injury combined are needed to induce Wnt signaling and promote the advanced tumor formation phenotype observed with HFD or DDC treated Sox9-Pten mice." (PMID 34083580, 2021). "According to our data, the SOX9 expression level was enhanced significantly in tumor tissues comparing to normal pituitary tissues (P = 0.019)." (PMID 33736633, 2021). "At 11–13 months when all of the Alb-Pten mice (48 out of 48) developed tumors, the tumor incidence of Sox9-Pten mice was only 63.6% (14 out of 22)." (PMID 34083580, 2021). "SOX9 is an important marker of acinar cell dedifferentiation and is indispensable for tumor formation in the pancreas." (PMID 33762742, 2021).
tumor (continued). "The SOX9 expression was detected around 2.3 times more in tumor tissues comparing to healthy pituitary tissues." (PMID 33736633, 2021). "Conclusively, these data indicate that SOX9 is aberrantly highly expressed in tumor tissues and predicts poor prognosis in CRC patients." (PMID 34124145, 2021). "We previously found that Reg IV overexpression upregulated SOX9 and promoted migration and invasiveness of tumor cells, while Reg IV silencing produced opposite results." (PMID 33639844, 2021). "Secondly, it is not surprising that overexpression of SOX9 in tumor tissue has been observed given the fact that SOX9 is a master transcription factor which is able to maintain cells in undifferentiated status and tends to be elevated during tumor genesis." (PMID 33681252, 2021). "High expression of SOX9 and TSPAN8 has been associated with tumor stage, poor prognosis and poor patient survival in PDAC." (PMID 34163029, 2021). "In line with the previous work, we observed that the number of CD8+ T cells decreased in the tumor samples of patients with high SOX9 expression, while the M2 macrophage abundance increased." (PMID 34778027, 2021). "Many studies showed that miR-30c-5p was downregulated in multiple tumor tissues and inhibited the proliferation/migration of tumor cells and the neovascularization of the tumor tissues by targeting SOX9/TGF-β." (PMID 33468212, 2021). "High-expression levels of SOX9 and TSPAN8 were associated with tumor stage, dismal prognosis and poor survival in PDAC." (PMID 34163029, 2021). "The SOX9 over-expression was detected in GH-secreting adenomas tumor tissues compared to normal pituitary tissues which were accompanied by overexpression of SOX9 protein in tumor tissues." (PMID 33736633, 2021). "In tumor sections, expression of Sox1, Sox9, and Map2 was obvious in undifferentiated cells and differentiated neural tissue." (PMID 33468253, 2021). "We observed a significant association between SOX9 expression and MCPyV-negativity (P < 0.001) and also between SOX9 expression and head and neck localization of the primary tumor (P = 0.039)." (PMID 34331569, 2021). "By inducing targeted deletion of tumor suppressor Pten in the SOX9+ adult liver cells, we report here that SOX9+ liver cells have the potential to function as liver TICs and fuel the formation of mixed-lineage tumors." (PMID 34083580, 2021). "In non-small cell lung cancer, TAMs secrete more TGF-β than other macrophage phenotypes and increases SOX9 expression, which strengthens tumor EMT, thereby increases tumor proliferation, migration and invasion." (PMID 33391402, 2021). "It was reported that ST6GAL1 induces the expression of the key tumor-promoting transcription factors Sox9 and Slug." (PMID 33836687, 2021). "Based on our data, the higher expression of SOX9 was detected in tumor tissues comparing to normal pituitary tissues." (PMID 33736633, 2021). "The data presented here clearly show that CDK9 inhibitors suppress the expression of Sox2 and Sox9, and interfere with anchorage independent growth of tumor cells." (PMID 34359807, 2021). "We first analyzed SOX9 expression, because rare SOX9-positive cells propagate tumor recurrence and metastasis in MB." (PMID 34192534, 2021). "Collectively, SOX9 plays critical roles in tumor development and progression, including tumor initiation, tumor microenvironment regulation, metastasis, and drug resistance." (PMID 34778027, 2021). "The strong expression of SOX9 in the selected tumor cells in the present case is thus related to their cartilaginous differentiation." (PMID 34513702, 2021). "To analyze if DNA hypomethylation suppresses intestinal tumorigenesis in Uhrf1ki/ki/ApcMin/+ mice by affecting tumor stem cells, we examined the levels of intestinal stem-cell marker genes Lgr5, Ascl2, and Sox9 by qRT-PCR." (PMID 33947834, 2021). "These inhibitors suppressed the expression of several genes like Sox2, Sox9, and Mcl1 that promote tumor growth, facilitating growth arrest." (PMID 34359807, 2021).